CCN2 (cellular communication network factor 2)
Diseases named in the same sentence as CCN2 in open-access papers (continued):
Sharing a sentence is not in itself a finding about the gene and the disease.
infection (28 papers, 2012 to 2025). The state of being infected such as from the introduction of a foreign agent such as serum, vaccine, antigenic substance or organism. "Porcine reproductive and respiratory syndrome virus (PRRSV) infection inhibited the mRNA transcription of CCN2 to facilitate virus replication." (PMID 36733771, 2022). "The YAP1/TAZ targets, CTGF/CCN2, and CYR61/CCN1 also showed upregulation, suggesting successful infection of human acinar cells with YAP15SA and TAZ4SA." (PMID 38247878, 2024).
cardiac disease (19 papers, 2006 to 2024). "Considering the pharmacological effects of Cu I against cardiac diseases, previous study showed that Cu I inhibit cardiomyocyte hypertrophy through inhibition of connective growth factor (CCN2) and transforming growth factor- (TGF-) β/SMAD signaling pathways." (PMID 29682157, 2018).
cardiovascular diseases (12 papers, 2014 to 2025). "Elevated levels of CCN2 are linked to several cardiovascular diseases." (PMID 39273564, 2024).
neurodegenerative disease (7 papers, 2014 to 2022). A disorder of the central nervous system characterized by gradual and progressive loss of neural tissue and neurologic function. "Interestingly, in neurodegenerative diseases, CCN2 elevation has been detected both in neurons and reactive astrocytes." (PMID 24551460, 2014). "Finally, the targeting of pro-fibrotic factors such as TGF-β, CTGF/CCN2 and platelet-derived growth factor (PDGF) signaling pathway might be a suitable therapeutic approach to improve muscle function in several degenerative diseases." (PMID 28520806, 2017).
retinopathy (7 papers, 2008 to 2021). "Although the in vivo biological relevance and activities, if any, of such a truncated variant remains to be determined, disease models of retinopathies seem to recapitulate a loss of function phenotype of the full CCN2/CTGF protein." (PMID 32429045, 2020). "The third gene in this group, Ctgf (or Ccn2, cellular communication network factor 2), plays a role in cell adhesion and was shown to be involved in oxygen-induced retinopathy-related neovascularization." (PMID 34404875, 2021).
inflammation (5 papers, 2014 to 2025). Aberrant reaction of the microcirculation characterized by movement of fluid and leukocytes from the blood into extravascular tissues. "Moreover, CCN2-induced kidney inflammation was prevented in RIPK3-deficient mice, indicating the key role of necroptosis in the inflammation induced by CCN2." (PMID 37627536, 2023). "TNF-α accelerates chronic pancreatic inflammation by positive regulation of CCN2 expression." (PMID 24722330, 2014).
vasculopathy (5 papers, 2013 to 2022). "Since CCN2/CTGF is highly susceptible to proteolytic degradation that commonly occurs during inflammatory reactions and vasculopathies, the manifestation of these diseases may actually recapitulate the tissue reaction to the loss of specific CCN2/CTGF signals." (PMID 32429045, 2020).
adenocarcinoma (3 papers, 2023 to 2025). A common cancer characterized by the presence of malignant glandular cells. "Mammosphere formation of MCF-7 adenocarcinoma cells, cell migration and gap closure following scratch wound of fibroblasts, induced by CCN2 were inhibited by CCN5 TSP1." (PMID 37245184, 2023). "TSP1 also inhibited other reported cell physiologic functions of CCN2 such as mammosphere formation of MCF-7 adenocarcinoma cells, cell migration and gap closure following scratch wound of fibroblasts." (PMID 37245184, 2023).
musculoskeletal disorders (3 papers, 2013 to 2023). "Although an anti-fibrosis treatment is greatly needed for humans with work-related or other musculoskeletal disorders, the anti-CCN2 drug used here has yet to be tested in humans for overuse-induced musculoskeletal disorders." (PMID 37762168, 2023).
neuromuscular disease (3 papers, 2021 to 2023). "Furthermore, the increased profibrotic factor CCN2-CTGF suggested a profibrotic mechanism shared with other neuromuscular diseases." (PMID 36675170, 2023). "Interestingly, the effects of blocking CCN2/CTGF in neuromuscular diseases are not limited to reduced fibrosis and improved skeletal muscle pathology but can also improve or protect neuronal inputs." (PMID 34435178, 2021). "Today, there are candidate therapeutic approaches that reduce CCN2/CTGF levels or activity, which improve muscle function and increase the quality of life of patients suffering from neuromuscular diseases." (PMID 34435178, 2021).
connective tissue diseases (2 papers, 2020 to 2025). "Moreover, from the table of top connective tissue disorders, the network of the term “Abnormality of cartilage tissue” for Epi C vs. Ctr group showed upregulation of collagens, biglycan (BGN), CCN2, and SRY-Box Transcription Factor 9 (SOX9)." (PMID 32575510, 2020).
skeletal dysplasia (2 papers, 2024 to 2025). Any Mendelian diseases that affects growth and development of the skeleton. "In ccn2a crispants, we observed skeletal developmental abnormalities similar to the phenotypes observed in patients with CCN2 variants which led to skeletal dysplasia and cleft palate." (PMID 39506047, 2025). "Alternatively, potential existence of differences in threshold effects of CCN2 deficiency for skeletal dysplasia between between mouse models and human remain to be clarified." (PMID 39414788, 2024). "Collectively, our study indicate that monoallelic variants in CCN2 lead to a human inherited skeletal dysplasia, and highlight the critical role of CCN2 in osteogenesis in human." (PMID 39414788, 2024).
immune diseases (1 paper, 2021). "Although CCN3 targeted therapy has not been used in clinical immune diseases, we believe that the application of the anti-CCN2 antibody in clinical trials will contribute to further clinical research of CCN3 to a certain extent." (PMID 34393649, 2021).
mitochondrial disease (1 paper, 2025). "A combined urinary biomarker panel—including stress markers (GDF15, CYCS, and PRDX2), immune effectors (MPO and C4A), ECM proteins (COL1A1 and CCN2), and selected amino acids—could support diagnosis, patient stratification, and longitudinal monitoring in mitochondrial disease." (PMID 41373442, 2025).
CCN2 also shares sentences with these, for which no sentence is quoted: glioblastoma (31 papers); glomerulosclerosis (31); Ureteral obstruction (17); diabetic retinopathy (13); atrial fibrillation (12); pulmonary arterial hypertension (10); cervical cancer (9); dilated cardiomyopathy (9); glomerulonephritis (9); acute kidney injury (8); esophageal squamous cell carcinoma (8); Glomerular sclerosis (8); neuroblastoma (7); papillary thyroid carcinoma (7); sarcoma (7); congestive heart failure (6); COVID-19 (6); end-stage renal disease (6); esophageal cancer (6); gallbladder cancer (6); hypertrophy (6); non-small cell lung carcinoma (6); pulmonary hypertension (6); trachoma (6); glomerular diseases (5); head and neck squamous cell carcinoma (5); Hepatitis (5); hypertrophic cardiomyopathy (5); IgA nephropathy (5); left ventricular hypertrophy (5).
A further 320 diseases each share a sentence with CCN2 in 5 papers or fewer.